AR (androgen receptor)
Diseases named in the same sentence as AR in open-access papers (continued):
Sharing a sentence is not in itself a finding about the gene and the disease.
prostate carcinoma (continued). "Also directly repressed by AR is ACOX2, a branched-chain acyl-CoA oxidase enzyme that takes part in the degradation of long branched fatty acid and bile acid intermediates in peroxisomes and is down-regulated in castration-resistant prostate cancer." (PMID 22849360, 2012). "Expression vectors for the human AR cDNA containing 9, 24, and 35 polyQ tracts and for AR cofactors, including ZMIZ1, ZMIZ2, and ARA70, were co-transfected with an androgen-induced luciferase reporter driven by a 7 Kb PSA promoter-enhancer fragment into prostate cancer cell line, DU145." (PMID 21949845, 2011). "Additionally, blockade of AR pathways attenuates FKBP5 expression, which is androgen dependent in prostate cancer cells, resulting in increased AKT phosphorylation due to a reduction in PHLPP protein levels since FKBP5 is a molecular chaperone for the AKT phosphatase PHLPP." (PMID 22110995, 2011). "The hypothesis has been supported by some recent studies indicating that androgen-refractory prostate cancer cells contain an apparent basal/stem cell-like signature, suggesting that these cancer cells may not be derived from the AR+ luminal cell population." (PMID 21241512, 2011). "In this study, we show that PBX3 is post-transcriptionally regulated by androgen in prostate cancer cells and that the effect might be independent of the androgen receptor." (PMID 21548940, 2011). "As monotherapy with an AR antagonist is not yet a standard treatment for patients with advanced or metastatic prostate cancer, it has been combined with medical (or surgical) castration, initially in studies conducted in the late 1980s and early 1990s (complete androgen blockade)." (PMID 22111003, 2011). "The same observation can be seen in the AR-negative prostate cancer cell lines, PC3 and DU145." (PMID 22110995, 2011). "These prostate cancer stem/progenitor cells are likely AR negative." (PMID 24212771, 2011). "The NLS signals did not function in AR-positive prostate cancer (LNCaP and 22RV1) cells, which might explain the localization of p44/WDR77 in the cytoplasm of these cells." (PMID 21789256, 2011). "However, we previously showed that Wnt-11 does not inhibit AR activity in androgen-independent AR-positive prostate cancer cell lines." (PMID 20219091, 2010). "Overall, this data supports increased AR activity in CRPC, which is consistent with re-expression of androgen-regulated genes as previously reported and similarity of expression of androgen regulated genes between CRPC and prostate cancer before androgen ablation." (PMID 20868494, 2010). "An important clinical corollary to these conclusions is that there exists a subtype of prostate cancers for which a more aggressive hormone therapy regimen or anti-AR therapy will elicit no clinical benefit, even though they possess AR mutation or amplification." (PMID 20628607, 2010). "Increased levels of expression of these genes may be indicative of the influence of adrenal androgens, or the local synthesis of androgen, to reactivate the AR to promote the progression of prostate cancer in the absence of testicular androgens." (PMID 20868494, 2010). "This may be because of the accumulation of ubiquitinated proteins and three proteasome target proteins, Bax, p27 and IκBα, in androgen receptor (AR)-negative PC-3 prostate cancer cells, which supports the conclusion that proteasome is inhibited by pristimerin." (PMID 22069560, 2010). "Moreover, as the majority of human prostate adenocarcinomas have this mature luminal phenotype, characterized by expression of cytokeratins 8/18, AR and prostate-specific antigen (PSA), the assumption has been that the cell of origin of prostate cancer is the differentiated secretory luminal cell." (PMID 19040209, 2009). "Its role in prostate cancer or its relationship with AR has not been studied." (PMID 19668381, 2009).
prostate carcinoma (continued). "Although we found that the CRD of sFRP1 is able to interact with each of four frizzled family members that are highly expressed in AR-expressing prostate cancer cell lines, sFRP1 repression of AR was not rescued by PTX treatment, indicating that G proteins are not involved in this phenomenon." (PMID 19277043, 2009). "This indicates that the mechanism of AR protein down-regulation by Wnt signaling may not exist in all prostate cancer cells." (PMID 18218096, 2008). "While the role of activated Wnt/β-Catenin signaling in prostate cancer is not entirely clear, recent evidence indicates that β-Catenin contributes to prostate cancer progression through its enhancement of the AR transcriptional activity in the presence of androgens." (PMID 18218096, 2008). "However, the key role of androgens and androgen receptor (AR), not just in early development but also in the progression of prostate cancer has now been demonstrated." (PMID 18673534, 2008). "However, the relationship between the AR and β-Catenin has not been examined in prostate cancer cells exposed to castration levels of androgens." (PMID 18218096, 2008). "The results indicate that caspase 8 and its downstream effectors participate in PL-induced apoptosis in prostate cancer cells, whether they express AR or not." (PMID 17262078, 2007). "Together, these data identify ERβ as a candidate effector of BPA action in prostate cancer cells expressing the AR-T877A mutant and demonstrate that BPA induces a unique transcriptional signature in prostate cancer cells that may be influenced by AR status." (PMID 18007998, 2007). "Moreover, activated STAT3 is believed to play a key role in androgen receptor activation in the absence of androgens, one explanation of hormone refractory growth of prostate cancer." (PMID 17712417, 2007). "However, the effect of Ebp1 on transactivation of wild-type AR in prostate cancer cells was not established." (PMID 15583694, 2005). "In the application to the prostate cancer dataset, we have found that two pathways, one modulated by androgen receptor and a second one by signals that originate from cell surface growth factor receptors, are prominently active in the organ-confined, non-metastatic prostate cancer samples analyzed." (PMID 16107210, 2005). "HRG has been previously shown to inhibit growth of AR+ but not AR− prostate cancer cell lines." (PMID 15583694, 2005). "Prostate cancer is one of these diseases, and particularly in patients with its advanced form, the lack of AR expression—either constitutive or induced in AR-positive cells by paracrine IL-1β signaling—might be compounded by the functional inactivation of the AR by ADT/ARIs." (PMID 39858071, 2025). "A particularly striking scenario is the bone metastatic niche in which prostate cancer cells, either lacking the AR or with this receptor inactivated by therapy, produce and secrete IL-1β, which is normally repressed by the binding of the AR to at least one ARE half-site near the IL-1β promoter." (PMID 39858071, 2025). "However, after 18 – 36 months of treatment, the androgen receptor (AR) signaling pathway is reactivated in the majority of patients, inevitably progressing to castration-resistant prostate cancer (CRPC), which makes prostate cancer much more aggressive and lethal." (PMID 40969278, 2025). "Bidirectional crosstalk between AR and epidermal growth factor receptor (EGFR) pathways further implicates therapeutic synergy, suggesting that androgen deprivation therapy (ADT), established in prostate cancer, may offer utility in AR+ TNBC either concurrently or sequentially." (PMID 41383624, 2025).
prostate carcinoma (continued). "Small cell neuroendocrine prostate cancer (SCNC) is an aggressive subtype of prostate cancer (PCa) defined by characteristic features such as a high nuclear to cytoplasmic ratio and indistinct cell borders, low or no expression of the androgen receptor (AR), and poor prognosis." (PMID 40723267, 2025). "Despite its toxicity concerns, CA does not engage significant pathways associated with prostate cancer, such as the androgen receptor (AR) and estrogen receptor (ER), suggesting that it may not directly influence prostate cancer progression through these receptors." (PMID 40429793, 2025). "Furthermore, SQLE overexpression demonstrates prognostic significance in advanced prostate cancer, where miR-205-mediated SQLE downregulation effectively suppresses de novo cholesterol synthesis, cellular proliferation, and resistance to next-generation androgen receptor inhibitors." (PMID 40722703, 2025). "Additionally, the switch in transcription factors from androgen receptor (AR) to glucocorticoid receptor (GR) modulated the persistent expression of TDO2, and the same TDO2-Kyn-AhR signalling pathway promoted the aggressive proliferation of prostate cancer cells in the ADT-resistant cell stage." (PMID 40759641, 2025). "Importantly, the mechanisms that enable prostate cancer cell adaptation to lack of AR signaling are poorly understood but could include transcriptional rewiring and cellular plasticity." (PMID 40952912, 2025). "AR splice variants lacking the LBD but retaining the N-terminal domain (NTD) and DNA-binding domain (DBD) remain constitutively active in the absence of androgen binding, thereby activating downstream signaling pathways and driving prostate cancer resistance and progression." (PMID 41079787, 2025). "Patients with ERα-expressing prostate cancers might best first be directed to treatments such as cytotoxic chemotherapy or radionuclide therapy rather than AR-targeted therapies, especially if residual serum or tissue levels of estrogen are sufficient to activate ERα." (PMID 39170834, 2024). "Inhibiting androgen receptor (AR) signaling through androgen deprivation therapy (ADT) reduces prostate cancer (PCa) growth in virtually all patients, but response may be temporary, in which case resistance develops, ultimately leading to lethal castration-resistant prostate cancer (CRPC)." (PMID 38383542, 2024). "Here, we have investigated the dynamics of TNT/cellular bridge and EV formation in prostate cancer cells, visualised the organelle cargo and exchange of AR between cancer and non-malignant cells, and examined some of the molecular machinery that may be involved in TNT/EV biogenesis." (PMID 39858418, 2024). "Thus, the effects of PIM1 on LD in prostate cancer are independent of AR or PTEN." (PMID 38097734, 2024). "Interestingly, prostate cancer in dogs is androgen insensitive and negative to androgen receptor." (PMID 38564578, 2024). "In addition to the Erk1/2–CREB signaling pathway, the PI3K–AKT–mTOR signaling pathway in prostate cancer and cGMP-PKG signaling pathway in the cardiovascular system also may be involved in AR-independent processes; however, their roles on synaptic function need to be further verified." (PMID 37991884, 2024). "In addition, we checked the growth of LNCaP and VCaP prostate cancer cells with the various sera, so that LNCaP and VCaP prostate cancer cells can be propagated by the sera, number 11, 12, and 18, and did not affect the AR-dependent transcriptional activity." (PMID 37744273, 2023). "However, in prostate cancer this is usually not the case and instead fatty acid synthesis is critical for transformation and tumorigenesis, with several key enzymes in this pathway directly being upregulated by the androgen receptor." (PMID 37529692, 2023).
prostate carcinoma (continued). "Type I and III of SRD5A coexist in prostate cancer cells to boost the AR pathway and support prostate cancer initiation and progression, thus downregulating either SRD5A1 or SRD5A3 may restrict the AR pathway and further inhibit the growth of prostate cancer cells." (PMID 37152995, 2023). "Lastly, further research, i.e., overexpressing ARHGEF2 in CRPC or enzalutamide-resistant models and using patient-derived organoids which harbor AR deletion, low AR activity or no AR expression models may be a more interesting way to demonstrate ARHGEF2 function in prostate cancer." (PMID 36335093, 2022). "Moreover, the fact that AR and CDC6-mediated DNA replication play a role in prostate cancers and their interaction alters the development of CRPC raises the potential for the utility of Remodelin in targeting DNA replication as a therapeutic approach in the treatment of prostate cancers." (PMID 35743017, 2022). "However, the prostate cancer progression molecular landscape is not solely defined by androgens and the AR, especially during later stages of the disease, as several other mechanisms come into play, such as WNT- and fibroblast growth factor (FGF)-related pathways." (PMID 35740556, 2022). "For example, a recent study demonstrated that miR-149 could inhibit AR expression and reduce the activity of PI3K/Akt1 signaling in castrate-resistant cells and also regulate RGS17-mediated oncogenic effects revealing its tumor suppressor nature in prostate cancer." (PMID 36091792, 2022). "Importantly, the effects of BAY1082439 on inhibition of cell proliferation and PI3K, IFNα and IFNγ pathways could be observed 24–48 h after a bullet dose on the Pten-null prostate cancer model in vivo without influence AR expression levels." (PMID 35013322, 2022). "Cell proliferation studies suggested that AR levels might influence the ability of prostate cancer cells to respond to metformin, for the AR-negative PC-3 cells were less sensitive to the anti-tumor effects of metformin than the AR-positive C4–2 and 22Rv1 cells." (PMID 36175875, 2022). "Therefore, further investigation of co-targeting reciprocal interactions of AR and IGF1 pathways between epithelial tumor cells and surrounding tumor niches may provide insight into potential therapeutic strategies for treating advanced prostate cancer." (PMID 36323713, 2022). "Besides, quantitative PCR and immunoblot analysis were also used to test whether DHT stimulation also inhibits ARHGEF2 expression in AR-negative prostate cancer cell lines (PC3 and DU145)." (PMID 36335093, 2022). "Several other therapeutic trials have focused on specific clinical markers to enrich for patients with “aggressive variant prostate cancer” (AVPC), though this clinical classification likely includes a mixture of tumor subtypes that may or may not be AR-driven." (PMID 35909568, 2022). "The occurrence of recurrent long amplicons encompassing more than just AR supports the hypothesis that KIF4A, AR, and possibly additional genes may be a ‘cluster’ of cancer driver genes that are co-amplified on the X-chromosome to drive prostate cancer tumorigenesis." (PMID 34326322, 2021). "Furthermore, LRRTM3 has no published connection to AR or prostate cancer." (PMID 33513133, 2021). "However, the majority of recurrent prostate cancers are neither completely hormone refractory nor androgen independent but are rather dependent on the AR signaling axis and alternate AR pathways have been found to support PCa growth through the reactivation and targeting of AR." (PMID 33800156, 2021). "While there have been efforts in standardizing histological diagnostic categorization for de novo as well as treatment-induced prostate cancer variants with NE/SC characteristics, some CRPC tumors that lost AR dependence may not show typical morphological and immunohistochemical characteristics." (PMID 34884545, 2021).
prostate carcinoma (continued). "Future studies are needed to understand whether AR has similar effects in neuron-like t-NEPC phenotype as in neurons, which molecular mechanisms contribute the phenotypic plasticity in t-NEPC cells and whether these phenomena have any role in maintaining treatment resistance in prostate cancer." (PMID 33572108, 2021). "Therefore, no FDA-approved treatment options are available for AR-null prostate cancer phenotypes." (PMID 33572730, 2021). "Moreover, this increase in CERK levels could represent an unprecedented target to curb prostate cancer aggressiveness, as demonstrated in AR-negative PC3 cells." (PMID 34503116, 2021). "In addition, broader evaluation of non–AR-driven resistance mechanisms, such as the recently described Double Negative Prostate Cancer classifier, may identify a distinct population of patients with different outcomes following treatment with ARSIs." (PMID 34197212, 2021). "Finally, we did not evaluate potential known interactions between androgen receptor blockade and downstream compounds, i.e., cAMP/PKA signaling, which may be involved in alternative pathways underlying castration-recurrent prostate cancer." (PMID 33451122, 2021). "In addition, PSA gene, which is a specific marker for prostate cancer under AR transcriptional control, results similarly upregulated upon β-HCH and testosterone treatment, whereas its mRNA levels decrease when cells are pre-treated with the AR antagonist bicalutamide." (PMID 33207735, 2020). "We found that in vitro treatment with a histone deacetylase inhibitor trichostatin A (TSA) could significantly increase the HNF4α expression in an androgen receptor (AR)-negative (PC-3) and two AR-positive (LNCaP, ARCaPM) prostate cancer cell lines in a time-dependent manner." (PMID 31695151, 2020). "Moreover, it was confirmed by a luciferase reporter assay that miR-205 directly binds to the 3′ UTR of AR and the ectopic expression of miR-205 decreased the expression of the receptor at mRNA levels but not much at protein levels in LNCaP prostate cancer cell line." (PMID 32854238, 2020). "An amplification loop may exist, as AR- cancers cells express high levels of IL-1β, while AR+ cells do not and androgen-deprivation drugs, that is, leuprolide and bicalutamide, inhibit prostate cancer cells’ mediated IL-1β secretion by peripheral blood mononuclear cells (PBMC) in vitro." (PMID 32635472, 2020). "In addition, Ack1 has also been shown to be critical for the progression of prostate cancer to the hormone therapy-insensitive stage, termed castration-resistant prostate cancer (CRPC) due to its ability to regulate the expression and function of androgen (AR) in an AR-independent manner." (PMID 32404161, 2020). "Likewise, edelfosine was able to induce apoptotic death in another two prostate cancer cell lines, LNCaP and VCap, through the differential regulation of p-AKT and activated transcription factor 3 (ATF3), respectively [two known regulators of androgen receptor (AR) activity]." (PMID 32708243, 2020). "However, the study did not address whether or not AR-axis induces global splicing changes in prostate cancer cells beyond those regulated by ESRPs." (PMID 32820253, 2020). "Thus, RSV reduces the AR protein levels but the reduction could not totally explain the suppression of AR function, as demonstrated in prostate cancer cell lines." (PMID 30832393, 2019). "For example, AR activity in prostate cancer cells may be modulated by RNAs, including the long non-coding RNA (lncRNA) HOTAIR, or by proteins, such as the transcriptional repressor RE1-silencing transcription factor (REST; also called neuron-restrictive silencer factor [NRSF])." (PMID 31116991, 2019). "As for PMEPA1, some studies have shown PMEAP1 inhibited proliferation through androgen receptor, however, androgen receptor and the related signalling pathways have been activated in prostate cancer, but maybe not in lung cancer or breast, or colorectal cancer." (PMID 30887697, 2019).